RNU6-1038P (RNA, U6 small nuclear 1038, pseudogene)
Gene: Small nuclear RNA gene on chromosome 18 (21,879,801 to 21,879,904, forward strand). Ensembl gene ENSG00000252325.
Homologues: Orthologues: chimpanzee U6 (97% identical), mouse Gm24925 (88% identical), dog U6 (84% identical). Paralogues in human: RNU6-116P (94% identical), RNU6-25P (94% identical), RNU6-33P (94% identical), RNU6-1 (93% identical), RNU6-140P (93% identical), RNU6-2 (93% identical), RNU6-3P (93% identical), RNU6-48P (93% identical), RNU6-4P (93% identical), RNU6-5P (93% identical), RNU6-6P (93% identical), RNU6-9 (93% identical), and 1288 more.